ALB (albumin)
Diseases named in the same sentence as ALB in open-access papers (continued):
Sharing a sentence is not in itself a finding about the gene and the disease.
dementia (continued). "Intravenous administration of albumin is beneficial to the improvement of daily function and attenuates the severity of the dementia in AD patients." (PMID 33013289, 2020). "The objectives of this study were to examine the change in the serum bilirubin and albumin concentrations of dementia patients with Aβ deposition, and to determine the effects of intravenous administration of albumin in the treatment of AD." (PMID 33013289, 2020). "Dementia patients had a lower body mass index (BMI) and erythrocyte count as well as lower serum albumin and total protein levels compared to controls." (PMID 32690030, 2020). "HGS showed a significant quartile-dependent difference in age (P < 0.01), BMI (P = 0.02), serum albumin (P < 0.01), creatinine (P < 0.01), calcium (P = 0.03), the presence of dementia (P = 0.02), CCI (P = 0.02), exhaustion (P = 0.03)." (PMID 31146702, 2019). "Greater age, lower serum albumin levels, higher C-reactive protein levels, and severe dementia were reported as poor prognostic factors after PEG." (PMID 31577813, 2019). "Multivariate analysis revealed male sex, cancer, advanced dementia and low serum albumin levels to be independent predictors of referral to exclusive palliative care." (PMID 29694607, 2018). "Nowadays, calculator websites are available to predict the mortality risk ofhemodialysis patients, providing information such as age, serum albumin, with orwithout dementia or peripheral vascular disease, and the answer to the surprisequestion." (PMID 29782631, 2018). "In this cohort, male sex, advanced dementia and low albumin levels were independent predictors of exclusive palliative care eligibility and were associated with significant clinical complications, such as delirium, infections and pressure ulcers." (PMID 29694607, 2018). "Gender, albumin, BMI, and dementia were all independent correlation factors for serum BChE activity." (PMID 28840123, 2017). "In PD patients, we found that dementia as well as gender, albumin, and BMI, was an independent correlation factor for BChE activity." (PMID 28840123, 2017). "Significant differences were found in age, serum urea nitrogen value, serum albumin value, and the degree of dementia." (PMID 31011042, 2017). "The finding that feeding intervention for dementia patients improved albumin and hemoglobin levels also supports the validity of assessing biochemical markers." (PMID 27336725, 2016). "Evidence for the impact of the diagnosis of dementia and decreasing serum albumin levels for patients receiving enteral nutrition is inconsistent." (PMID 25854831, 2015). "No further studies have explored the correlation between serum albumin and pressure sores in patients with dementia receiving enteral nutrition." (PMID 25854831, 2015). "Significant risks in meta-analysis were age, dementia, severe illness, poor vision, urinary catheters, polypharmacy and low albumin." (PMID 24610863, 2014). "Our pooled analysis confirmed statistically significant associations for dementia, illness severity (mean APACHE II score), urinary catheterisation, polypharmacy, albumin level and length of hospital stay." (PMID 24610863, 2014). "The aim of the present study was to investigate if ApoE genotypes are associated with BBB function (estimated by cerebrospinal fluid-serum albumin ratio) in a large cohort of patients with different types of dementia." (PMID 24386372, 2013). "In the present study we investigated for the first time if ApoE genotypes are associated with BBB dysfunction estimated by cerebrospinal fluid-serum albumin ratio in a cohort of patients with different types of dementia." (PMID 24386372, 2013). "In the literature other biomarkers indicating differences between AD and VaD have been described, such as albumin index and the CSF/Serum folate ratio, where a reduced folate ratio was found to be a characteristic of dementia with vascular component." (PMID 22701795, 2012).
dementia (continued). "Variables that were statistically significant (p<0.05) in the univariate analysis were age, gender, Parkinsonism, dementia, arrhythmia, body height, waist circumference, vision acuity, Karnofsky score, serum hemoglobin and albumin level." (PMID 21526155, 2011). "CSF-serum albumin ratio was also found to be higher in elderly depressed women and in patients suffering from dementias compared to age-matched controls." (PMID 19936105, 2009). "Skoog found higher CSF/serum albumin ratios in several types of dementia including AD and vascular dementia indicating an impairment of the BBB." (PMID 17983474, 2007). "Over 50% (54.14%) of the subjects in our study had some form of dementia, 13.43% had DM, 6.82% had albumin levels lower than 2.5 g/dL 10.71% had experienced aspiration episodes before PEG placement, 550.50% had a BMI lower than 21 kg/m2, and almost 79.41% of subjects had comorbidities." (PMID 39275209, 2024). "Further research examining specific subtypes of dementia could yield additional insights into the role of albumin in different forms of dementia." (PMID 39206288, 2024). "In addition, plasma exchange with albumin replacement was shown to slow cognitive and functional decline in AD, suggesting the therapeutic effect of albumin in dementia." (PMID 39206288, 2024). "In this study, CSF ANGPT-2 level was highest in MCI patients and correlated with CSF albumin and sPDGFRβ, a marker of pericyte injury that was previously shown to be elevated in early AD (clinical dementia rating 0.5) and to correlate with MRI evidence of BBB breakdown within the hippocampus." (PMID 38182581, 2024). "Hypokalemia occurred earlier in patients with low albumin, low potassium, and dementia." (PMID 38868417, 2023). "Patients with low serum albumin levels, low serum potassium levels, and dementia before yokukansan may develop hypokalemia early." (PMID 38868417, 2023). "Given that the GNRI is calculated based on actual/ideal weight and serum albumin level, this index system is simple to apply and can be used even for individuals who have difficulty answering a questionnaire, such as those with dementia or an uncooperative attitude." (PMID 36890183, 2023). "According to clinical research, the dementia patients serum albumin level was significantly lower." (PMID 37576498, 2023). "Second, findings from a study showed that ALB has a defensive role in the process of inflammation and infection, and substantial evidence suggests that inflammatory mechanisms are critical players in the pathogenesis of dementia, including AD." (PMID 36313027, 2022). "Moreover, a recent study showed that intravenous supplementation with human ALB improved daily function and reduced dementia burden in patients with AD." (PMID 36313027, 2022). "Bilirubin and albumin concentrations in dementia patients with Aβ deposition were examined." (PMID 33013289, 2020). "Significantly higher indirect bilirubin (IBIL) concentrations, lower albumin concentrations, and higher ratio of IBIL to albumin (IBIL/ALB) were observed in dementia patients with Aβ deposition, including AD, dementia with Lewy bodies, and general paresis of insane." (PMID 33013289, 2020). "Whether the prevention of kidney function deterioration, and restoration of albumin and hemoglobin may help to slow or halt cognitive deterioration in oldest old patients with dementia requires further study." (PMID 33028210, 2020). "In this study, a comparison of baseline characteristics between the groups before propensity score matching revealed that patients with greater age, lower serum albumin levels, higher C-reactive protein levels, and severe dementia were more likely to receive TPN." (PMID 31577813, 2019). "In addition, measurements of albumin in the CSF and serum of AD and non-dementia patients excluded the possibility that dysfunction of the blood/CSF barrier influenced the level of cytokines in the CSF in the current cohort of AD patients (data not shown)." (PMID 27671345, 2016).
dementia (continued). "All three stepwise selection approaches revealed older age, male gender, and the number of catheters and drainages as predictors for delirium, independent of possible confounders (i.e., age, gender, SAPS II, SAS, SOFA scores, dementia and/or leukoencephalopathy, and albumin serum levels)." (PMID 27797086, 2016). "The hypothesis is that the increase in albumin levels could be related to a release toward the bloodstream in order to maintain the dynamic equilibrium of Aβ between the brain and blood plasma, as Aβ is increased in several dementia conditions." (PMID 37190655, 2023). "Age, dementia at admission, Charlson Comorbidity Index, and several laboratory findings, such as white blood cell counts, lactate dehydrogenase level, total protein level, albumin level, blood urea nitrogen level, C-reactive protein level, and fibrinogen level differed between the two groups." (PMID 37240566, 2023). "However, we found an assertive evidence that bilirubin-induced neurotoxicity in dopaminergic neuron-like cells was decreased by increasing the concentration of serum, and intravenous administration of human albumin to AD patients benefited on their daily function and dementia severity." (PMID 33013289, 2020). "For these reasons, we suggest that the cisterno-lumbar gradients of protein, albumin and markers of neurodegenerative diseases in the spinal canal may be similar in elderly patients with dementia irrespective of its cause." (PMID 27581842, 2016). "Finally, AGE-albumin could be an excellent biomarker and a therapeutic target for alcohol-induced neuronal death and possibly dementia." (PMID 25140518, 2014). "In the current study, CSF/serum albumin ratio was higher in the SSVD and mixed dementia groups compared with the control group." (PMID 37980667, 2023). "In the ≥80 group, risk-factors affecting perioperative mortality, included ASA score, pre-operative albumin, creatinine, WBC levels, cancer etiology, ADL dependency, and dementia." (PMID 37048549, 2023). "The cerebrospinal fluid (CSF)/serum albumin ratio (Qalb), an indicator of BBB permeability, was measured in a total of 95 hospitalized dementia patients." (PMID 37213537, 2023). "The nomogram was constructed by three predictors, including dementia, chronic obstructive pulmonary disease (COPD), and albumin level." (PMID 35783136, 2022). "The nomogram constructed by dementia, COPD, and albumin level can be conveniently used to predict POD in patients with elderly hip fractures." (PMID 35783136, 2022). "The six variables were further identified by stepwise backward logistic regression analysis, and three of them (dementia, COPD, and serum albumin level) were screened for optimal prediction model establishment." (PMID 35783136, 2022). "Compared with department 1, the proportions of dementia, pulmonary infection, and COPD was higher, the level of albumin was lower, and the operative duration was longer in the patients in department." (PMID 35783136, 2022). "Dementia, COPD, and serum albumin levels were the key predictors for POD in elderly patients with hip fractures." (PMID 35783136, 2022). "In this study, all the three predictors, including dementia, COPD, and albumin, were easy to obtain objectively and reliably." (PMID 35783136, 2022). "While identifying factors that influence survival in older adults with advanced dementia following PEG tube insertion, a cohort study reports advanced age and higher baseline serum albumin as strong predictors of mortality and survival, respectively." (PMID 31929906, 2019). "Similarly, in this study, high heterogeneity was observed in age, cognitive impairment, dementia, MMSE score, albumin and TSH levels, length of hospital stay, and duration of the procedure." (PMID 40168626, 2025). "The nomogram was constructed by three variables, including dementia, COPD, and serum albumin level." (PMID 35783136, 2022).
dementia (continued). "The results showed that age, senile dementia, hypothyroidism, WBC, PCT, ALB, and prolonged bed rest were related to occult pulmonary infection, and that advanced age, senile dementia, hypothyroidism, and prolonged bed rest were independent risk factors for occult pneumonia." (PMID 34901268, 2021). "The serum amyloid P component values were significantly higher in individuals with dementia, independent of serum albumin content measured as a control for plasma in the cortex samples." (PMID 34671726, 2021). "It has been postulated a connection between dementia and blood-brain barrier (BBB) dysfunction, which could lead to altered CSF/serum albumin index due to the BBB disruption." (PMID 32645849, 2020). "Within the dementia group, erythrocyte count (r = 0.669, p = 0.002) and albumin (r = 0.707, p < 0.002) showed a significant positive correlation with MMSE and clock drawing test showed a weak positive correlation with albumin (r = 0.485, p = 0.019)." (PMID 32690030, 2020). "Variables such as medical history of aspiration pneumonia and dementia, use of dentures, NT-proBNP, TLC, BUN, CRP, albumin, transthyretin, MMSE, handgrip strength, prehospital MSAS and MSAS, MPT, and prehospital BI and BI, were entered into a multivariate model." (PMID 27898735, 2016). "A CCT evaluated diet and environmental modification, increased nurse time and assistance at meals in 19 malnourished Italian dementia unit residents, finding increased serum albumin (3.0 to 3.4 g/dL at 18 months) but no changes in weight or BMI." (PMID 26801619, 2016). "One study found serum albumin levels did not predict survival in patients with dementia, but did predict survival in patients without dementia receiving enteral nutrition." (PMID 25854831, 2015). "Other studies which analyze multiple parameters (albumin ratio and common CSF biomarkers for dementia) are not available." (PMID 25147945, 2014). "Subjects with B6 deficiency were statistically significantly older, were less physically active (steps per day), had lower levels of s-ALAT and s-albumin, higher levels of homocysteine and used less sedatives/hypnotics, selective serotonin reuptake inhibitors (SSRI) and anti-dementia drugs." (PMID 23394203, 2013). "RDA showed that BMI, albumin, total protein, sCD14, statins, NSAIDs, number of drugs, MNA-SF, MMSE, clock-drawing test, sex, number of drugs were explanatory variables for microbiome composition in controls compared to dementia and between different stages of cognitive dysfunction (p < 0.1)." (PMID 32690030, 2020). "A retrospective study at a tertiary academic center of 392 patients who underwent PEG tube placement, including 165 patients with dementia showed that neither short-term nor long-term mortality improved, these patients had a shorter time to death and had no improvement in albumin." (PMID 31281761, 2019). "Comparison of "dementia" and "non-dementia" groups for body mass index and serum albumin level." (PMID 29682231, 2018). "Our present measurements of albumin content in the neocortex samples show that the quantities of SAP that are present, and that correlate with dementia status, are not just the result of non-specific leakage through the blood barrier." (PMID 34671726, 2021). "Third, higher plasma levels of AST (>40IU/L) and albumin (<35g/L) but lower levels of calcium (<2.1mmol/L) and potassium were observed in DMD patients than in DM patients without dementia." (PMID 32805719, 2020). "Interestingly, nondemented women who developed dementia during the research follow-up had an initial higher CSF-serum albumin ratio compared to those who did not develop the disease, suggesting BBB dysfunction may precede the clinical symptoms and be related to the pathogenesis of the disease." (PMID 19936105, 2009).
dementia (continued). "However, measuring the cerebrospinal fluid/plasma albumin ratio an indicator of BBB permeability, Janelidze and Colleagues reported that the ratio was increased in all dementias compared with controls, but is not related to APOE genotype." (PMID 37467176, 2023). "Statistically significant differences were found between the groups with and without white nails with respect to age, albumin concentration, BMI, hemoglobin level, FIM score, home discharge, CCI, duration of the previous hospitalization, readmission, brain infarction, and dementia." (PMID 35602847, 2022).